NLRP3 (NLR family pyrin domain containing 3)
Diseases named in the same sentence as NLRP3 in open-access papers (continued):
Sharing a sentence is not in itself a finding about the gene and the disease.
cholestasis (continued). "Dysregulated BA signaling drives cholestasis, NAFLD, and IBD by disrupting FXR-mediated anti-inflammatory pathways and promoting NLRP3 inflammasome activation via TGR5 suppression." (PMID 40458398, 2025). "MCC-950 is thus far the best investigated, direct, potent, selective and small-molecule inhibitor of NLRP3 and was shown to ameliorate NASH fibrosis and liver damage in chronic stages of cholestasis in mice." (PMID 34685598, 2021). "Rats with cholestasis induced by ANIT was used to evaluate the protective effects and mechanism of PF by regulating SIRT1/FXR and NF-κB/NLRP3 signaling pathway." (PMID 34512782, 2021). "In conclusion, our findings proved that calcipotriol suppressed the NLRP3 signal by activating YAP1 to alleviate liver injury and retard fibrogenesis in cholestasis." (PMID 32296329, 2020). "In a previous study, we proved that NLRP3 inhibition by MCC950, a selective NLRP3 inhibitor, can significantly alleviate liver injury and retard the development of fibrosis in bile-duct-ligation (BDL)-induced cholestasis in mice." (PMID 32296329, 2020). "Taken together, our findings provide direct evidence that excessive CDCA can serve as endogenous danger signal to activate NLRP3 inflammasome by TGR5/EGFR signaling and promoting ATP release, therefore, identifying a new mechanism by which inflammation is initiated during cholestasis." (PMID 27924062, 2016).
coronary atherosclerosis (27 papers, 2016 to 2025). Atherosclerosis of the coronary vasculature. "Expression of the NLRP3 inflammasome in atherosclerotic plaques and in peripheral blood monocytes in patients with acute coronary syndrome were associated with coronary atherosclerosis and adverse cardiac events." (PMID 33804661, 2021). "In patients with coronary atherosclerosis, increased levels of both IL-27 and NLRP3 inflammasome components are reported and are also associated with disease severity." (PMID 29176764, 2017). "The NLRP3 inflammasome has also been linked to the onset of coronary atherosclerosis." (PMID 31354731, 2019). "In conjugation with the WGCNA results, we speculate that NLRP3 inflammasome expression was associated with high blood glucose and may play a role in the pathogenesis of coronary artery atherosclerosis." (PMID 30941060, 2019). "Clinical evidence has shown that the level of NLRP3 from peripheral blood monocyte is highly associated with the severity of coronary atherosclerosis in patients, especially NLRP3 inflammasome has been observed to localize in the cytoplasm of foam cells and macrophages." (PMID 30405440, 2018). "However, NLRP3 in subcutaneous adipose tissue has been associated with the severity of coronary atherosclerosis." (PMID 29245937, 2017). "We revealed a inverse association between serum Treg/Th17 ratioand NLRP3 level in individuals with coronary atherosclerosis, indicating thatNLRP3 may act as a promoter in the initiation and progression of atheroscleroticplaques by modulating the Treg/Th17 ratio." (PMID 39076663, 2022). "Patients with coronary atherosclerosis present with increased mRNA and protein levels of NLRP3, ASC, caspase-1, IL-1β and IL-18 in atherosclerotic plaques, the amount of NLRP3 correlating with disease severity." (PMID 37239938, 2023). "Previous report proved that high NLRP3 inflammasome expression in the aorta was identified in the patients with coronary atherosclerosis, and the NLRP3 expression was correlated with the severity of coronary artery stenosis." (PMID 36627567, 2023). "In this study, we reported an abnormallyhigh level of serum NLRP3 in patients with coronary atherosclerosis, whichroughly matches with those seen in earlier investigations, reconfirming thepathogenic potential of NLRP3 in atherogenesis." (PMID 39076663, 2022). "In another study, patients with acute coronary syndrome showed increased peripheral blood monocyte NLRP3 protein level, which showed a correlation with the severity of coronary atherosclerosis." (PMID 36406365, 2022). "Patients with coronary atherosclerosis show increased NLRP3 expression in blood monocytes, mainly during an acute coronary event." (PMID 35055149, 2022). "In humans, high expression of NLRP3 inflammasome components has been detected in carotid atherosclerotic plaques and high levels of expression of NLRP3 correlate with the severity of coronary artery atherosclerosis." (PMID 35890291, 2022). "Zheng and Xing found that coronary atherosclerosis patients expressed high levels of NLRP3 in the aorta, which was correlated to heart disease severity." (PMID 36438901, 2022). "For example, in the context of stable atherosclerotic disease it has been demonstrated that components of NLRP3 inflammasome are highly expressed in carotid atherosclerotic plaques and that high levels of expression of NLRP3 correlate with the severity of coronary artery atherosclerosis." (PMID 36768804, 2023). "In chronic coronary syndromes, NLRP3 is correlated with the severity of coronary atherosclerosis." (PMID 35055149, 2022). "IL-1β and NLRP3 have been positively correlated with the extent of coronary atherosclerosis as assessed by SYNTAX score and CLINICAL SYNTAX score, while NLRP3 has also been positively correlated with the GENSINI score and lesion characteristics of coronary syndrome patients." (PMID 34685553, 2021).
coronary atherosclerosis (continued). "Moreover, the expression of NLRP3 in SAT also positively correlated with the severity of coronary atherosclerosis suggesting that NLRP3 inflammasomes in SAT could be engaged in atherogenesis." (PMID 38612394, 2024). "NLRP3 can interact with TLR and be recently found to slow the progression of coronary atherosclerosis in the absence of NLRP3 inflammatory vesicles." (PMID 37773705, 2023).
glaucoma (27 papers, 2018 to 2026). Increased pressure in the eyeball due to obstruction of the outflow of aqueous humor. "NLRP3-IL-1β inflammasome cascade is a critical pathway in neuroinflammatory response and has been implicated in retinal degenerative conditions including glaucoma." (PMID 37542647, 2023). "NLRP3 inflammasome, a crucial driver of inflammation, is a multiprotein molecular complex implicated in several neuroinflammatory diseases including glaucoma." (PMID 37542647, 2023). "Nucleotide-binding leucine-rich repeat-containing receptor family, pyrin domain containing 3 (NLRP3) inflammasome, an innate immune signaling receptor regulating inflammatory responses, is closely associated with neuroinflammation in glaucoma." (PMID 36289519, 2022). "For example, the mitochondria-associated adaptor molecule, MAVS, is required for NLRP3 inflammasome activity as it promotes the recruitment of NLRP3 to the mitochondria and the subsequent IL-1β production in vivo, however, this has yet to be shown in glaucoma." (PMID 34366851, 2021). "Furthermore, in a mouse model of acute glaucoma, activation of NLRP3 inflammasome was found to be required for RGCs death and inflammation, indicating that NLRP3 inflammasome plays a key role in RGCs loss and neuroinflammation in glaucoma." (PMID 36289519, 2022). "The literature for this review was identified through searches of PubMed, Web of Science, and Scopus using combinations of the terms 'glaucoma', 'complement', 'inflammasome', 'NLRP3', 'microglia', and 'neuroinflammation'." (PMID 41900887, 2026). "Consistent with our findings, previous studies have shown that microglia can aggravate retinal inflammation and RGCs damage via activation of the NLRP3 inflammasome in glaucoma models." (PMID 41601638, 2026). "Recent evidence highlights the NACHT, LRR and PYD domains-containing protein 3 (NLRP3) inflammasome as a critical mediator bridging biomechanical stress and neuroinflammation in glaucoma." (PMID 40486511, 2025). "The HMGB1/NLRP3 axis is crucial in the progression of ocular diseases, particularly in retinal damage and glaucoma." (PMID 40688353, 2025). "The increased release of HMGB1 regulates NLRP3 activation through an NF-κB-dependent mechanism, contributing to retinal damage and potentially progressing to glaucoma." (PMID 40688353, 2025). "Elevated levels of NLRP3 inflammasome components have been identified in the trabecular meshwork, retina, and optic nerve head of eyes affected by glaucoma." (PMID 38562304, 2024). "Recent research has compellingly demonstrated the activation of the NLRP3 pathway in different types of glaucoma." (PMID 38562304, 2024). "Consistently, it has been reported that RGC damage is substantially suppressed in NLRP3 knockout mice even when the optic nerve is damaged in experimental animal models of glaucoma." (PMID 38983051, 2023). "Glutamate excitotoxicity via N-methyl-d-aspartic acid (NMDA) receptors plays a vital role in RGCs death in glaucoma, which is often accompanied by oxidative stress and NLRP3 inflammasome activation." (PMID 36289519, 2022). "Based on these studies, we consider that NLRP3-dependent IL-1β plays a crucial role in inflammation and RGCs death in the glutamate-induced glaucoma model, while the exact pathway by which it triggers inflammation is worthy of further investigation." (PMID 36289519, 2022). "In our study, we demonstrated the intrinsic necroptotic pathway and NLRP3 inflammasome axis in R28 cells and RGCs in the glutamate-induced excitotoxic glaucoma model." (PMID 36289519, 2022). "Previous studies have shown that increased mRNA and protein levels of IL-1β, a signal of NLRP3 inflammasome activation, were observed in the blood of glaucoma patients." (PMID 36289519, 2022). "Pro-inflammatory cytokines resulting from NLRP3 inflammasome activation are increased in the blood of patients with glaucoma, resulting in the death of RGCs due to neurotoxic inflammation." (PMID 35836195, 2022).
glaucoma (continued). "In this regard, lactate-mediated HCA1R activation was shown to reduce various inflammatory markers, such as NLRP3 and interleukin (IL)-1β, in a mouse model of glaucoma." (PMID 35805182, 2022). "IOP elevation activates NLRP3 in the glial cells of the retina, leading to neurotoxic inflammation, axon degeneration, and subsequent death of RGCs in glaucoma." (PMID 35836195, 2022). "Specifically, the NLRP3 inflammasome, a key driver of pyroptosis and inflammation, has been demonstrated to engage in glaucoma pathogenesis." (PMID 35836195, 2022). "The NOD-, LRR- and pyrin domain-containing protein 3 (NLRP3) inflammasome is particularly important to inflammatory signaling in glaucoma." (PMID 34366851, 2021). "Additional studies are now required to further investigate current and novel inhibitors of the NLRP3 inflammasome pathway for glaucoma treatment." (PMID 34439904, 2021). "This review discusses glaucoma as an inflammatory disease and evaluates targeting the NLRP3 inflammasome as a therapeutic strategy." (PMID 34439904, 2021). "The NLRP3 inflammasome is expressed in the eye and its activation is reported in pre-clinical studies of glaucoma." (PMID 34439904, 2021). "One study has shown that the NLRP3 inflammasome, caspase-1, and caspase-8 are increased in human glaucoma compared to normal eyes." (PMID 34925047, 2021). "The NLRP3 inflammasome is the most widely studied within a glaucoma context, and involvement involves both priming and activation steps." (PMID 34366851, 2021). "NLRP1 and NLRP3 inflammasomes seem to be involved in the pathogenesis of glaucoma in models of acute glaucoma, and, to date, only one study has demonstrated the presence of NLRP3 inflammasome in human glaucomatous eyes." (PMID 33953963, 2021). "Currently, this is the only study that has evaluated a NLRP3-specific inhibitor in an inducible model of glaucoma." (PMID 34439904, 2021). "Clinical studies have observed an upregulation level of IL-1β mRNA and protein expression in the blood of glaucoma patients, suggesting activation of the NLRP3 inflammasome in glaucoma." (PMID 34925047, 2021). "Further studies will be necessary to elucidate the precise link between the KATP channel, the P2X7 receptor, NLRP3 inflammasome activation and cellular metabolic crisis in glia vs. neurons during glaucoma." (PMID 34366851, 2021). "Neuroinflammation has been shown to play a key role in glaucoma and, specifically, the NLRP3 inflammasome, a key driver of inflammation, has recently been implicated." (PMID 34439904, 2021). "Increased levels of IL-1β mRNA and protein have also been observed in the blood of glaucoma patients compared with controls, suggesting activation of the NLRP3 inflammasome in glaucoma." (PMID 34439904, 2021). "Notably, activation of the NLRP3 inflammasome in microglia has been implicated in RGC damage and is now regarded as a key driver of neuroinflammation in glaucoma." (PMID 41601638, 2026). "The key role of NLRP3 inflammasome activation in glaucoma has been highlighted, leading to increased pro-inflammatory cytokine release and creating a chronic inflammatory environment in the retina, which can exacerbate RGC loss and contribute to neurodegeneration." (PMID 40528237, 2025). "Mechanical stress, a common factor in glaucoma, may serve as a trigger for NLRP3 inflammasome activation, resulting in the release of pro-inflammatory cytokines." (PMID 38562304, 2024). "The potential therapeutic implications of targeting the NLRP3 pathway in glaucoma are promising." (PMID 38562304, 2024). "NLRP3 inflammasome activation has been reported in pre-clinical studies of glaucoma." (PMID 35836195, 2022). "Nevertheless, the exact mechanisms of NLRP3 inflammasome activation in the progression of glaucoma remain unknown and need to be further studied." (PMID 36289519, 2022).
glaucoma (continued). "In addition to stress/damage sensors (e.g., TLRs and NLRP3) and inflammatory transducers (e.g., MyD88 and NF-κB), effectors and amplifiers of inflammation are also upregulated in glaucoma." (PMID 33953963, 2021). "Collectively, these studies provide evidence that NLRP3 inhibition may be a novel therapeutic strategy to protect RGCs and prevent axon degeneration in glaucoma." (PMID 34439904, 2021). "The NLRP3 inflammasome therefore appears to be a strong target for therapy development in glaucoma." (PMID 34439904, 2021). "A hypothetical mechanism for the action of the NLRP3 inflammasome in glaucoma is presented." (PMID 34439904, 2021). "In fact, mechanical strain of astrocytes, as might occur in optic nerve head glial cells in glaucoma, can trigger the NLRP3 inflammasome." (PMID 30424795, 2018). "Therefore, our data suggests that the ketogenic diet exerts its anti-inflammatory response in glaucoma not only through the inhibition of AMPK-NF-κB signaling but also via induction of HCAR1-mediated inhibition of NLRP3 inflammasome." (PMID 30424795, 2018). "Furthermore, it has also been found that chronic subclinical inflammatory reactions caused by oral bacteria that contain LPS in their outer membrane aggravate glaucoma, suggesting a possible involvement of LPS in NLRP3 inflammasome-mediated inflammatory reactions in glaucoma." (PMID 38983051, 2023). "Thus, inhibition of NLRP3 inflammasome may be a potential strategy to prevent RGCs death in glaucoma." (PMID 36289519, 2022). "Thus, we could infer that the RIP1/RIP3/MLKL pathway contributes to glutamate-induced NLRP3 inflammasome activation, and it may be one of the upstream regulators of NLRP3 inflammasome activation in glaucoma." (PMID 36289519, 2022). "Therefore, it is necessary to investigate the interactions occurring between necroptosis and NLRP3 inflammasome activation in glaucoma, which may provide a promising target for RGCs protection and neuroinflammatory attenuation." (PMID 36289519, 2022). "Recently, the nucleotide-binding oligomerization domain, Leucine rich Repeat and Pyrin domain containing protein 3 (NLRP3) inflammasome, has gained attention as a potential key orchestrator of inflammation in the aetiology of glaucoma, and may be an attractive therapeutic target." (PMID 34439904, 2021). "Therefore, pharmacologically targeting NLRP3 may serve as a neuroprotective therapy to prevent the progression of glaucoma." (PMID 34439904, 2021). "NLRP3 may be a promising IOP independent target for the treatment of glaucoma." (PMID 34439904, 2021). "Additionally, in a mouse model of glaucoma, the KD was associated with increased expression of ARRB2 and its interacting protein and BHB target HCA1, which led to reduced levels of NLRP3 and IL-1β, consistent with inhibited NLRP3 inflammasome function." (PMID 34888340, 2021). "Using the microbead-induced mouse model of glaucoma, we also show an induction of genes associated with each of these pathways at 4 weeks post-microbead injection, specifically C3 and C1Q (complement cascade), TLR4 (Toll-like receptor pathway), TNFα (TNFα pathway), and NLRP3 (inflammasome pathway)." (PMID 31570110, 2019). "In a glaucoma model, high expression of GPR81 in retinal microglial cells and astrocytes reduced the formation of the NLRP3 inflammasome." (PMID 40650086, 2025). "Ketogenic diet therapy addresses the energy requirements of glaucoma patients and inhibits the inflammatory response by activating the lactate-GPR81 signalling pathway and inhibiting AMPK/NF-κB signalling and NLRP3 inflammasome activation." (PMID 38755659, 2024). "Since TXNIP mediates inflammatory responses by binding the NLRP3 inflammasome, we also used intravitreal injection of MCC950, an NLRP3 inhibitor, to indirectly observe the relationship between TXNIP and neuropathy in glaucoma." (PMID 39736512, 2024).